KALRN (kalirin RhoGEF kinase)
Diseases named in the same sentence as KALRN in open-access papers:
KALRN is named in the same sentence as 47 diseases in open-access papers, as found by Europe PMC text mining. Sharing a sentence is not in itself a finding about the gene and the disease. The quoted sentences say what the papers report.
schizophrenia (16 papers, 2012 to 2024). A major psychotic disorder characterized by abnormalities in the perception or expression of reality. "KALRN was also linked with schizophrenia risk through genetic analyses of rare variants—along with depression —and through postmortem analyses of cortical KALRN mRNA and protein levels within individuals with autism." (PMID 39408648, 2024). "In particular, P2255T in KALRN was significantly associated with schizophrenia (OR = 2.09, p = 0.048) in a Japanese population." (PMID 37958606, 2023). "Variants in genes upstream of the Rho GTPase family, such as KALRN and p250GAP, have been reported to be associated with schizophrenia." (PMID 37958606, 2023). "A transcriptome-wide association study in patients with schizophrenia revealed an increase in exon skipping immediately prior to the GEF2 domain in KALRN transcripts." (PMID 37958606, 2023). "The KALRN genomic locus is implicated in several neurodevelopmental and neuropsychiatric diseases, including autism, schizophrenia, bipolar disease, and intellectual disability." (PMID 36649036, 2023). "A rare missense mutation in the KALRN gene has been shown to be a genetic risk factor for schizophrenia." (PMID 22548195, 2012). "Mutations in the KALRN gene that are deleterious to protein function are associated with several neurodevelopmental diseases like autism and intellectual disability, as well as neuropsychiatric diseases like schizophrenia." (PMID 36649036, 2023). "In addition, some missense variants in KALRN, such as P2255T and T1207M, showed a higher frequency in schizophrenia cases compared to control cases." (PMID 37958606, 2023). "The KALRN gene has been linked to schizophrenia and adult attention deficit-hyperactivity disorder." (PMID 28706949, 2017). "Importantly, a sequence variant of KALRN found in schizophrenia patients encodes a Kalirin-7 mutant with diminished Rac GEF activity, and this mutant fails to increase spine density and size." (PMID 25879033, 2015). "Evidence of under-expression of KALRN in comorbid conditions like schizophrenia was also reported, both at the mRNA and at the protein expression level in postmortem brains of patients." (PMID 39408648, 2024). "Recently, several variants of RhoA-associated GAPs, including ARHGAP10, ARHGAP18, and p250GAP, and GEFs such as KALRN and ARHGEF11, were reported to be significantly associated with the development of schizophrenia." (PMID 37958606, 2023). "KALRN protein (kalirin) isoforms show increased expression in adolescence and early adulthood when schizophrenia and many MAPK supercluster AB-like tumors occur." (PMID 35440587, 2022). "KALRN, TRIO, and DISC1 misexpression or mutation are implicated in attention deficit hyperactivity disorder, autism, bipolar disorder, schizophrenia, and other conditions." (PMID 35440587, 2022). "RAC1 can be also involved in the pathogenesis of schizophrenia as the downstream signaling hub molecule for the proteins encoded by risk genes such as DISC1, KALRN, and TIAM1." (PMID 34943902, 2021). "For example, the KALRN gene, which encodes proteins with two Rho-GEF domains, has been associated with stroke, early onset coronary artery disease, schizophrenia and adult attention deficit-hyperactivity disorder." (PMID 23116210, 2012). "Decreased KALRN mRNA levels were reported in the prefrontal cortex of subjects with schizophrenia, and PPI deficits due to altered sensory motor gating have been reported in schizophrenic patients and psychosis-prone individuals." (PMID 23116210, 2012). "A first attempt was made to carry out a multi-trait genetic association analysis between PD age at onset and MPV, which revealed novel associations in interesting candidate genes such as KALRN (Kalirin RhoGEF Kinase), encoding a PINK1 interactor previously implicated in schizophrenia, AD and PD." (PMID 36672180, 2023).
schizophrenia (continued). "The KALRN gene has been linked to neurodevelopmental disorder risk, with mutations in KALRN implicated in schizophrenia, ASD, developmental delay, and intellectual disability linked to hereditary homozygous loss of KALRN-expression." (PMID 36533124, 2022). "Moreover, KALRN expression is decreased in schizophrenia patients, and Kalirin-7 interacts with several schizophrenia-related proteins." (PMID 25879033, 2015).
coronary artery disease (7 papers, 2017 to 2023). "It is relevant to thrombosis that KALRN and associated SNPs confer increased risk of ischemic stroke, atherosclerosis and early-onset coronary artery disease." (PMID 32438682, 2020). "Interestingly, polymorphisms in the KALRN gene have been associated with an increased risk of both cerebrovascular and cardiovascular diseases, including ischemic stroke and coronary artery disease." (PMID 38132326, 2023). "Moreover, KALRN was downregulated in the heart tissue of patients affected by both DCM and ischemic cardiomyopathy, and mutations within KALRN have been associated with the promotion of stroke and coronary heart disease." (PMID 36292100, 2022).
autism (6 papers, 2019 to 2025). Persistent deficits in social interaction and communication and interaction as well as a markedly restricted repertoire of activity and interest as well as repetitive patterns of behavior.
Intellectual disability (5 papers, 2016 to 2023). "Exome sequencing provided initial evidence linking KALRN to monogenic intellectual disability in man, and we propose that KALRN is the causative gene for the autosomal recessive phenotype in this family." (PMID 27421267, 2016).
atherosclerosis (4 papers, 2018 to 2022). A disease characterized by the build-up of fatty material and calcium deposition in the arterial wall resulting in partial or complete occlusion of the arterial lumen. "Some mutated genes are related to atherosclerosis, such as FAAH, KALRN, ATP10D, CUBN, APOA5, and LRP1." (PMID 36071494, 2022). "KALRN genetic variations may lead to endothelial dysfunction and atherosclerosis through influence on the Rac-1 signaling pathway, which is associated with Type 2 diabetic." (PMID 32671063, 2020). "Based on these clarifications, there are several hypotheses that genetic variations in KALRN result in endothelial dysfunction and atherosclerosis." (PMID 30483314, 2018). "The roles of KALRN in the development of atherosclerosis are not evidently characterized in the literature." (PMID 30483314, 2018).
asthma (3 papers, 2012 to 2022). "Evidence for an involvement of KALRN is further supported by the finding of a nominal association with a single-nucleotide polymorphism in KALRN in our previously published GWAS of childhood asthma." (PMID 23046476, 2012). "Of these ten, variants in three genes (PDE4DIP, CBLB, and KALRN) were deemed of particular interest based on their functional prediction scores and previously reported function or asthma association." (PMID 23046476, 2012). "Three of these genes (PDE4DIP, CBLB, and KALRN) are of increased interest based on either their function or previous work in asthma." (PMID 23046476, 2012). "For the KALRN associated region the maximum Δβ was at cg23440058 and signified a decrease in methylation of 48% at cg23440058 in airway epithelial cells isolated from individuals with asthma versus those without asthma." (PMID 31595000, 2019). "Differential DNA methylation of the same KALRN and WNT7B associated regions were not identified in airway epithelial cells isolated from individuals with and without asthma via pronase digestion (E respectively)." (PMID 31595000, 2019). "In particular, two regions associated with the KALRN and WNT7B promoters had a difference in DNA methylation between airway epithelial cells isolated from individuals with asthma versus those without asthma of greater than 40% (mean Δβ 0.46 and 0.45 respectively)." (PMID 31595000, 2019).
depression (3 papers, 2021 to 2025). "This association was mainly driven by a factor representing somatic/neurovegetative symptoms, suggesting a more prominent implication of KALRN in somatic forms of depression, which is often characterized by treatment resistance." (PMID 39408648, 2024). "Therefore, KALRN may represent a potential candidate for both clinical and experimental studies on somatic and treatment-resistant depression." (PMID 39408648, 2024).
endothelial dysfunction (3 papers, 2018 to 2024). In vascular diseases, endothelial dysfunction is a systemic pathological state of the endothelium (the inner lining of blood vessels) and can be broadly defined as an imbalance between vasodilating and vasoconstricting substances produced by (or acting on) the endothelium. "In contrast, the 2D hPSC-ECs and HMVEC-Cs upregulated genes associated with LECs and, alongside 3D hPSC-ECs, expressed genes implicated in endothelial dysfunction (KALRN, POSTN, FN1, respectively)." (PMID 38775849, 2024).
ischemic stroke (3 papers, 2017 to 2023). A stroke disorder caused by obstruction of blood flow to the brain, due to thrombotic (local blood clot formation) or embolic (due to a blood clot or other material traveling from another site) event. "Our results provide evidence that KALRN gene variations were associated with ischemic stroke in the Chinese Han population." (PMID 28706949, 2017). "In this study, we investigated possible associations between 3 polymorphisms of the KALRN gene and ischemic stroke in a northern Chinese Han population." (PMID 28706949, 2017). "Thus, the aim of the present study was to investigate if KALRN SNPs were associated with ischemic stroke among Han Chinese." (PMID 28706949, 2017).
glioma (2 papers, 2020 to 2023). A benign or malignant brain and spinal cord tumor that arises from glial cells (astrocytes, oligodendrocytes, ependymal cells). "Most of the CSF samples procured from GBM patients showed the presence of TA autoantibodies against NOL4 and KALRN while low grade glioma samples showed an antigenic response against UTP4 and CCDC28A." (PMID 33415070, 2020). "Proteins NOL4 (a cancer-testis antigen) and KALRN showed an antigenic response in the CSF of GBM patients, whereas, UTP4 and CCDC28A showed an antigenic response in low grade gliomas when compared with the control samples." (PMID 33415070, 2020). "KALRN, EIF1AD, DLL1, SH3RF1, and TLN1 are involved in neuronal structural integrity, plasticity, differentiation, and may contribute to the highly invasive nature of GBM as compared to other gliomas." (PMID 36834486, 2023).
sarcoidosis (2 papers, 2018 to 2020). Sarcoidosis is a multisystemic disorder of unknown cause characterized by the formation of immune granulomas in involved organs. "Our finding further establishes that the NOD2 2722G > C variant in combination with variants for IL17RA, EPHA2 and KALRN genes could play a significant role in the development of sarcoidosis." (PMID 29554915, 2018). "Combination of polymorphisms in the NOD2, IL17RA, EPHA2 and KALRN genes could play a significant role in the development of sarcoidosis by maintaining a chronic pro-inflammatory status in macrophages." (PMID 29554915, 2018). "Remarkably, in addition to NOD2 2722G > C, three single nucleotide variants for the IL17RA, KALRN and EPHA2 genes were found in the family X patients with sarcoidosis." (PMID 29554915, 2018). "Taken together, our data suggest a functional and pathogenic link between EPHA2, KALRN and IL17RA in the occurrence of the disease of family X sarcoidosis patients, acting in addition to the NOD2 functional defect." (PMID 29554915, 2018).
amyotrophic lateral sclerosis (1 paper, 2025). Amyotrophic lateral sclerosis (ALS) is a neurodegenerative disease characterized by progressive muscular paralysis reflecting degeneration of motor neurons in the primary motor cortex, corticospinal tracts, brainstem and spinal cord. "Notably, proteins significantly decreased under high CE burden included canonical STMN2, ELAVL3, and KALRN, as well as kinesin proteins that are genetically associated with amyotrophic lateral sclerosis." (PMID 40501554, 2025).
breast carcinoma (1 paper, 2019). "Additional recurrently mutated genes detected in the 16 PALB2-associated breast cancers profiled by WES included CTNNA2, TMPRSS13, KRTAP4–11, LAMA5, KALRN, and COLL22A1 (all, n = 3)." (PMID 31428676, 2019).
Cognitive impairment (1 paper, 2016). Abnormal cognition is characterized by deficits in thinking, reasoning, or remembering. "The role of KALRN in causing cognitive impairment in human and the full phenotypic spectrum will be established when other families with ID show pathogenic variants in KALRN and the exact molecular pathophysiology is understood." (PMID 27421267, 2016).
developmental delay (1 paper, 2022). "Here we show that a single point mutation within the Rac1-GEF PH domain of KALRN, found in a patient with developmental delay, results in loss of catalytic activity." (PMID 36533124, 2022).
epilepsy (1 paper, 2024). A brain disorder characterized by episodes of abnormally increased neuronal discharge resulting in transient episodes of sensory or motor neurological dysfunction, or psychic dysfunction. "In addition to NDDs such as ASD, KALRN variants have also been implicated in epilepsy." (PMID 39596051, 2024).
Epileptic encephalopathy (1 paper, 2018). A condition in which epileptiform abnormalities are believed to contribute to the progressive disturbance in cerebral function. "The top-ranked probes related to 25 genes including HNRNPL, RASSF5, CD3D and KALRN involved in immune signalling pathways, in addition to TBC1D24, FBXO9 and VIPR2 previously linked to epileptic encephalopathy." (PMID 29484035, 2018).
human papilloma virus infection (1 paper, 2023). An infectious process caused by a human papillomavirus. "One study showed that KALRN is mutated in some cases of human papilloma virus infection concomitant with oropharyngeal squamous cell carcinoma." (PMID 37884919, 2023).
hyperthyroidism (1 paper, 2014). Overactivity of the thyroid gland resulting in overproduction of thyroid hormone and increased metabolic rate. "Borderline significant signals were observed at BACH2- rs10944479 with a higher risk of increased TSH levels as well as overt hyperthyroidism (P = 0.011 and P = 0.012), and at the KALRN-rs2010099 SNP with a lower risk of decreased TSH levels (P = 0.010)." (PMID 24586183, 2014).
melanoma (1 paper, 2022). A malignant, usually aggressive tumor composed of atypical, neoplastic melanocytes. "Furthermore, the reported TMB-related genes including PAPPA2, KALRN, and TTN were significantly correlated with patient response in NSCLC, which were also identified in melanoma." (PMID 36139377, 2022).
mood disorder (1 paper, 2021). A cognitive disorder a disturbance in which the person's mood is hypothesized to be the main underlying feature. "We seized on the genes HCRT, KALRN, and HTR2A to substantiate the connection to mood disorders." (PMID 34987393, 2021).
open-angle glaucoma (1 paper, 2021). Chronic outflow obstruction of the eye's drainage canals that can lead to increased internal eye pressure and optic nerve damage. "The KALRN gene (rs1392912) was identified to be a potential susceptibility genetic marker of primary open-angle glaucoma (POAG) progression in Malays." (PMID 34804680, 2021).
primary angle-closure glaucoma (1 paper, 2021). An angle-closure glaucoma characterized by closure of the anterior chamber angle by an intrinsic defect such that aqueous outflow is blocked and the intraocular pressure becomes inappropriately elevated leading to optic nerve damage and visual field loss. "PLEKHA7, ABCC5, and KALRN have been identified as susceptible genetic markers related to glaucoma." (PMID 34804680, 2021). "We aimed to investigate the association between the identified susceptible genetic markers PLEKHA7 rs11024102, ABCC5 rs17217796, and KALRN rs1392912 in the progression of primary angle-closure glaucoma (PACG) in Malay patients." (PMID 34804680, 2021). "Increased expression and/or activity levels of RhoGEF (KALRN) proteins could augment contractile activation of the smooth muscles, which could reduce the supply of blood to the optic nerve head and result in glaucoma progression." (PMID 34804680, 2021).
tumor (4 papers, 2020 to 2023). "Accordingly, enhanced tumor mutational burden was associated with KALRN mutations in six independent patient cohorts." (PMID 37794585, 2023). "Further, we examined the promoter methylation levels of DELMRGs and found that several genes (such as OAS2, KALRN, SLC16A7, PER2) had significantly lower methylation levels in tumor samples, while several genes (SLC6A3, CDO1, and SERPINC1) were significantly higher methylated." (PMID 37795453, 2023). "KALRN, MCF2/Dbl, NGEF/EPHEXIN, ARHGEF7/βPix/COOL-1, CDC42EP2, DOCK9, NET1, TIAM2, ABR, PLEKHG5, RhoBTB2 and PREX1 were identified as being increased at the tumour rim." (PMID 33256106, 2020).
cardiovascular disease (2 papers, 2012 to 2023). "The human KALRN gene, which encodes a complex, multifunctional Rho GDP/GTP exchange factor, has been linked to cardiovascular disease, psychiatric disorders and neurodegeneration." (PMID 23116210, 2012).
brain diseases (1 paper, 2024). "This evidence underscores the importance of studying epigenetic variation within the KALRN gene and the role that it may play in brain diseases, particularly in atypical depression, which is often characterized by somatic symptoms." (PMID 39408648, 2024).
KALRN also shares sentences with these, for which no sentence is quoted: Stroke (4 papers); attention deficit-hyperactivity disorder (3); cancer (3); alcohol abuse (1); alcoholics (1); Alzheimer disease (1); Anxiety (1); Ascites (1); autism spectrum disorder (1); bipolar disorder (1); bladder cancer (1); ischemic cardiomyopathy (1); metabolic syndrome (1); neuroblastoma (1); neurodegenerative disease (1); neurodevelopmental disorder (1); oropharyngeal squamous cell carcinoma (1); psychiatric disorder (1); psychosis (1); pulmonary sarcoidosis (1); thyroid disease (1).